METAP2 (methionyl aminopeptidase 2)
Diseases named in the same sentence as METAP2 in open-access papers (continued):
Sharing a sentence is not in itself a finding about the gene and the disease.
neuroblastoma (3 papers, 2009 to 2020). Neuroblastoma (NB) is the most common solid, extracranial childhood tumor. "METAP2 is reported to be responsible for promoting cell proliferation in SH-SY5Y neuroblastoma cells and for exhibiting immune-modulatory activity." (PMID 32397415, 2020). "A800141, another orally active inhibitor of MetAP2, showed potent anti-angiogenic and anti-tumor activities in several tumor xenografts including neuroblastoma, B-cell lymphoma, and colon and prostrate carcinomas." (PMID 21876694, 2012). "TNP-470, an irreversible inhibitor of MetAP2, showed anti-angiogenic activity in preclinical models of neuroblastoma." (PMID 21876694, 2012). "Another reversible inhibitor of MetAP2 is A-357300, which is a promising therapeutic agent against neuroblastoma." (PMID 21876694, 2012). "MetAP2 is a cytoplasmic enzyme responsible for promoting endothelial cell proliferation, migration, and induction of angiogenesis in neuroblastoma." (PMID 21876694, 2012). "The concentration of MetAP2 has been found to be higher in neuroblastomas." (PMID 21876694, 2012). "The anti-angiogenic inhibitors of methionine aminopeptidase (MetAP2) may hold a key role in therapeutic management of neuroblastoma." (PMID 21876694, 2012). "The angiogenesis inhibitor TNP470, O-(chloro-acetyl-carbamoyl) fumagillol, a synthetic analogue of fumagillin, suppressed the expression of MetAP2 in human neuroblastoma and thus, MetAP2 may be an important molecular target for human neuroblastomas." (PMID 19703310, 2009).
Alzheimer disease (2 papers, 2023 to 2025). A progressive, neurodegenerative disease characterized by loss of function and death of nerve cells in several areas of the brain leading to loss of cognitive function such as memory and language. "As a proof-of-concept study, Autotacs were designed, synthesized, and demonstrated to induce the lysosomal degradation of a set of oncoproteins such as androgen receptor, estrogen receptor β, MetAP2, and BRD4 as well as tau aggregates in Alzheimer’s disease (AD)." (PMID 37355598, 2023).
amebiasis (2 papers, 2013 to 2023). A parasitic infectious disorder caused by amoebas. "The observation may indicate that the structure of the fumagillin-binding pocket of EhMetAP2 might be different from that of human MetAP2, and suggest the possibility of developing highly selective fumagillin analogues against amebiasis." (PMID 37874291, 2023).
cholangiocarcinoma (2 papers, 2014 to 2019). A carcinoma that arises from the intrahepatic biliary tree (intrahepatic cholangiocarcinoma) or from the junction, or adjacent to the junction, of the right and left hepatic ducts (hilar cholangiocarcinoma). "Overexpression of MetAP2 had been also related with B cells of malignant lymphomas of various subtypes, and with cholangiocarcinoma (CAA) cells." (PMID 31861936, 2019). "In addition, it significantly reduced cholangiocarcinoma cell proliferation in a dose-dependent manner and the degree of growth inhibition was dependent on the amount of cellular MetAP2." (PMID 24595456, 2014).
colorectal adenocarcinoma (2 papers, 2009 to 2022). The most common type of colorectal carcinoma. "Earlier, we demonstrated the high expression of MetAP2 in colorectal adenocarcinoma patients." (PMID 19703310, 2009).
diabetes (2 papers, 2019 to 2022). "Our list is supported by colocalization of genes known to lead to Mendelian forms of diabetes (e.g., SLC2A2 and WFS1) and of genes with previously demonstrated mechanisms of association with IR/T2D (e.g., METAP2, PLEKHA1 [TAPP1], FAM13A, and KLF14)." (PMID 35292083, 2022).
glioblastoma (2 papers, 2022 to 2025). The most malignant astrocytic tumor (WHO grade IV). "Analogous assays targeting MetAP2 revealed that fumagillin-105 more efficiently inhibited the migration of U87-MG glioblastoma cells as early as 4 h and up to 24 h post-scratch." (PMID 35173167, 2022). "Fumagillin-105 exhibited DC50 of ~0.7 μM for MetAP2 in HEK293 cells with Dmax, 24 hr of ~1–10 μM and DC50 of ~500 nM in U87-MG glioblastoma cells." (PMID 35173167, 2022).
hepatocellular carcinoma (2 papers, 2009 to 2022). A malignant tumor that arises from hepatocytes. "Anti-sense of MetAP2 also induces apoptosis in rat hepatoma cells." (PMID 19703310, 2009).
Insulin resistance (2 papers, 2017 to 2025). Increased resistance towards insulin, that is, diminished effectiveness of insulin in reducing blood glucose levels. "METAP2, which showed strong association with the 46 traits (p-value ≤ 2.62 × 10−20), HOMA-B (p-value ≤ 3.14 × 10−32), HOMA-IR (p-value ≤ 3.17 × 10−17) and insulin (p-value ≤ 8.61 × 10−10), has demonstrated associations with insulin resistance and insulin levels." (PMID 29040274, 2017).
leukemia (2 papers, 2021 to 2023). A malignant (clonal) hematologic disorder, involving hematopoietic stem cells and characterized by the presence of primitive or atypical myeloid or lymphoid cells in the bone marrow and the blood. "On the other hand, METAP2 inhibitors have been shown to induce apoptosis in leukemic cell lines, which renders them potent therapeutic agents also for leukemia." (PMID 34502231, 2021). "Moreover, we found that some genes are also important for leukemia development (Jarid2, Metap2, Jak3, Pla2G15, Zfp384, Casp8 and Dpf2)." (PMID 37700325, 2023).
lung carcinoma (2 papers, 2020 to 2022). "In contrast to Metap2, Metap1-specific inhibition is relatively rarely investigated but was shown to have anti-tumor effects in cervical cancer and fibrosarcoma cells 65, as well as in human umbilical vein endothelial cells and human lung carcinoma cells." (PMID 35673573, 2022).
Thromboembolism (2 papers, 2023 to 2025). The formation of a blood clot inside a blood vessel that subsequently travels through the blood stream from the site where it formed to another location in the body, generally leading to vascular occlusion at the distant site. "Other medications such as sibutramine, a norepinephrine and serotonin inhibitor, lorcaserin, a serotonin 2C receptor agonist, and beloranib, a methionine aminopeptidase 2 (MetAP2) inhibitor, were discontinued due to significant adverse events of thromboembolism and other safety concerns." (PMID 37780616, 2023).
Arthritis (1 paper, 2007). Inflammation of a joint. "It has been reported that fumagillin and other molecules that may act by inhibiting MetAP-2 reduce arthritis in animal models." (PMID 18072970, 2007).
COVID-19 (1 paper, 2022). A disease caused by infection with severe acute respiratory syndrome coronavirus 2. "Among them, six (ADK, DHFR, METAP2, PIN4, SC5D, and TMEM263) had matching risk factor genes showing consistent patterns, i.e., transcriptional downregulations increased the COVID-19 mortality risk." (PMID 35547187, 2022).
endothelial dysfunction (1 paper, 2026). In vascular diseases, endothelial dysfunction is a systemic pathological state of the endothelium (the inner lining of blood vessels) and can be broadly defined as an imbalance between vasodilating and vasoconstricting substances produced by (or acting on) the endothelium. "SNHG5 promotes METAP2 expression by sponging miR-377-3p, leading to increased IL-8 secretion and endothelial dysfunction." (PMID 41769044, 2026).
fungal infection (1 paper, 2018). "The NMT1/2 and MetAP2 genes’ targeting miR-132-5p was found to be associated with fungal infection of human dendritic cells with Candida albicans and Aspergillus fumigatus and regulates immune responses through the interactions with FKBP1B, KLF4, and SPN genes." (PMID 29579063, 2018).
liver cancer (1 paper, 2022). An epithelial or non-epithelial malignant neoplasm that arises from the liver. "Only one study in liver cancer cells that overexpress constitutively active Akt1/PKB-α showed a 1.5-fold higher METAP2 activity compared to wildtype cells indicating that the pathway somehow regulated Metap2 activity." (PMID 35673573, 2022).
malaria (1 paper, 2017). Malaria is a serious and sometimes fatal disease caused by a parasite that commonly infects a certain type of mosquito which feeds on humans. "Fumagillin and its synthetic analogs thereby irreversibly inhibit the methionine aminopeptidase-2 (MetAP2), making them promising therapeutic candidates against malaria parasites, trypanosomes, or other amoebae." (PMID 29259922, 2017).
malignant lymphomas (1 paper, 2009). "Higher MetAP2 expression was reported in malignant mesothelioma, malignant lymphomas and esophageal squamous carcinomas." (PMID 19703310, 2009).
melanoma (1 paper, 2022). A malignant, usually aggressive tumor composed of atypical, neoplastic melanocytes. "A biodegradable NP consisting of poly-lactic-co-glycolic acid (PLGA) improved cellular uptake and increased the anti-cancer activity of methionine aminopeptidase 2 (MetAp2) inhibitor AD-3281 to melanoma." (PMID 36015256, 2022).
mesothelioma (1 paper, 2009). A usually malignant and aggressive neoplasm of the mesothelium which is often associated with exposure to asbestos. "It has been demonstrated that there is a high expression of MetAP2 in human mesothelioma tissue, and the association of this expression with anti-apoptotic function in those neoplastic cells." (PMID 19703310, 2009). "In addition, the inhibition of MetAP2 expression in mesothelioma cells leads to cell death and that such apoptosis is avoided in cases where there is overexpression of Bcl-2." (PMID 19703310, 2009).
osteosarcoma (1 paper, 2023). A usually aggressive malignant bone-forming mesenchymal neoplasm, predominantly affecting adolescents and young adults. "DNA hypermethylation of BMP1, methionyl aminopeptidase 2 (METAP2), matrix metalloproteinase (MMP) 11, and BTB domain and CNC homolog 1 (BACH1) gene promoter was also observed in fluoride-exposed human osteosarcoma cells." (PMID 37371586, 2023).
pancreatic cancer (1 paper, 2024). "Seven genes were identified in mass spectrometry and bioinformatic analysis, all significantly downregulated in pancreatic cancer (GEO data, GSE32676), including TSPYL2, TSR1, METAP2, CYR61, EBF2, CIRBP, and TGFBR3." (PMID 38015024, 2024).
pancreatic endocrine tumors (1 paper, 2021). "This may be conservative as we found literature evidence that the genes in the top perturbed gene pair of the visual phototransduction control pathway, METAP2‐FNTA, play roles in oncogenic progression in rhabdomyosarcoma and pancreatic endocrine tumors, respectively." (PMID 34698427, 2021).
prion disease (1 paper, 2018). A transmissible disease that is caused by a protein that is able to induce abnormal folding of normal cellular proteins, leading to characteristic spongiform brain changes, which are associated with neuronal loss without an inflammatory response. "On the other hand, a similar analysis for miRNAs that target MetAP2 gene revealed regulation of fatty acid biosynthesis, signaling pathways regulating pluripotency of stem cells, ErbB signaling pathway and prion diseases as the top KEGG pathways involved." (PMID 29579063, 2018).
pulmonary fibrosis (1 paper, 2012). Chronic progressive interstitial lung disorder characterized by the replacement of the lung tissue by connective tissue, leading to progressive dyspnea, respiratory failure, or right heart failure. "We have previously found that inhibition of MetAP2 with fumagillin in bleomycin-injured mice decreased pulmonary fibrosis by selectively decreasing the proliferation of lung myofibroblasts." (PMID 22509410, 2012).
pulmonary hypertension (1 paper, 2012). Increased pressure within the pulmonary circulation due to lung or heart disorder. "To determine if MetAP2 gene expression is increased in the lungs of patients with pulmonary arterial hypertension, we performed quantitative RT-PCR on lung samples from patients with IPAH (n = 6) compared to normal controls (n = 6)." (PMID 22509410, 2012). "By immunohistochemistry, we found that MetAP2 was expressed in the lesions of human pulmonary arterial hypertension." (PMID 22509410, 2012).
renal carcinoma (1 paper, 2023). A carcinoma arising from the epithelium of the renal parenchyma or the renal pelvis. "In parallel, inhibition of MetAP2 activity by M8891 was studied in renal cancer xenografts in mice by measuring accumulation of Met-EF1α, a substrate of MetAP2." (PMID 37798538, 2023).
Thrombocytopenia (1 paper, 2025). A reduction in the number of circulating thrombocytes. "Thrombocytopenia is anticipated to be a drug class effect, as it has also been observed in a recent clinical trial of a non–fumagillin-based, reversible METAP2 inhibitor." (PMID 40444533, 2025).
cancer (30 papers, 2007 to 2026). A tumor composed of atypical neoplastic, often pleomorphic cells that invade other tissues. "Increased expression of METAP2 gene is associated with various forms of cancer, and thus methionine aminopeptidase 2 inhibitors (MetAP2) were initially developed for treatment of cancer by preventing tumour proliferation." (PMID 35464063, 2022). "Increased expression of METAP2 is associated with various forms of cancer and it has been investigated as a cancer drug target over the last two decades." (PMID 35286297, 2022). "In one of the first studies, PROTACs containing phosphopeptide IkappaB (IκB) have been shown to recruit the SCFβ-TrCP Ub ligase complex, subsequently promoting the degradation of methionine aminopeptidase 2 (MetAP-2), which has been linked to cancer." (PMID 36046115, 2021). "Our findings indicate that several miRNAs that target myristoylation related genes (NMT1/2 and MetAP2) are associated with cancer." (PMID 29579063, 2018). "Taken together, the predicted data strongly support the association of miRNAs targeting NMT1/2 and MetAP2 genes to signaling pathways implicated in cancer and immune response." (PMID 29579063, 2018). "MetAP2 stimulates cancer cell proliferation when it is upregulated and appears to play an essential role in tumor progression." (PMID 42031914, 2026). "This phase I dose-escalation study investigated the safety and tolerability of evexomostat (SDX-7320), an optimized METAP2 inhibitor, in 32 patients with heavily pretreated, late-stage cancer with a variety of solid tumors and metabolic states." (PMID 40444533, 2025). "METAP2 inhibitors have previously been clinically shown to have antitumor and antimetastatic effects in patients with late-stage cancer, as well as resensitizing patients to chemotherapy when combined with such agents." (PMID 40444533, 2025). "F53B6.5 is a predicted ortholog of human methionyl aminopeptidase 2 (METAP2), which removes methionine residues from nascent polypeptide chains and are also implicated in cancer." (PMID 36404134, 2023). "In humans, analogues of fumagillin represent potential anti-cancer agents, including some in clinical trials, where inactivation of MetAP2 inhibits angiogenesis crucial to tumour growth." (PMID 33601283, 2021). "It has been shown that MetAP2 has a crucial role in angiogenesis, which is why MetAp2 inhibitors have been used in cancer treatment." (PMID 35126141, 2021). "We found that cancer-related lymphangiogenesis is inhibited in murine models following MetAp2 inhibition treatment." (PMID 32708166, 2020). "Here based on our previous study and the present study, we show that high expression of CHD1L plays a potential role in the inducement of EOC cancer cell invasion and/or metastasis via the regulation of METAP2 expression." (PMID 32922205, 2020). "MetAP2 inhibitors markedly decrease the anchorage-independent growth of cancer cells by more than 90%." (PMID 32456226, 2020). "On the other hand, fumagillin has anti-angiogenic activity, probably because of its inhibitory activity against the MetAP2 enzyme; consequently, it has valuable pharmaceutical potential and a potential role in the treatment of cancer." (PMID 31861936, 2019). "Higher concentration of MetAP2 in cancer cells compared to normal cells suggests that this enzyme plays an important role in cell proliferation and tumour growth." (PMID 30567416, 2018). "It was found that the most significantly enriched pathway regulated by miRNAs that target both NMT1/2 genes and the MetAP2 gene was proteoglycans in cancer." (PMID 29579063, 2018). "In vitro studies on anti-cancer activity showed that compound 17 strongly inhibited MetAP2 activity and its anti-proliferative effect was confirmed by studies on human umbilical vein endothelial cells (HUVEC)." (PMID 30567416, 2018).
cancer (continued). "Here, we performed a global characterization of the N-terminal methionine excision pathway and the inhibition of MetAP2 by fumagillin in a number of lines, including cancer cell lines." (PMID 27542228, 2016). "TNP-470 is an angiogenesis inhibitor (mediated by its irreversible binding to methionine aminopeptidase-2 (MetAP2)) that has been investigated as an anti-cancer drug." (PMID 25652463, 2015). "METAP2 is also an interesting drug target in cancer and other diseases." (PMID 37085483, 2023). "MetAP2 is reported to be a therapeutic target for cancer and obesity." (PMID 32456226, 2020). "Taken together, our data suggest that MetAp2 is a mediator of both angiogenesis and lymphangiogenesis and that its inhibition may slow cancer progression and metastasis." (PMID 32708166, 2020). "The role of MetAP2 on cell proliferation, and therefore on cancer, has also been widely studied." (PMID 31861936, 2019). "The enzyme methionine aminopeptidase-2 (MetAP-2) is thought to play an important function in human endothelial cell proliferation, and as such provides a valuable target in both inflammation and cancer." (PMID 18072970, 2007). "Therefore, it was possible to establish a link between cancer and inhibition of the MetAPs through the proto-oncogene c-Src and likely other oncogenes, which represent substrates for both MetAP1 and MetAP2, and, in this way, to justify the antitumoral effect of the bengamides." (PMID 35736176, 2022). "MetAp2 may prove to be an effective target for both angiogenesis and lymphangiogenesis, and its inhibition may be used one day to supplement current methods for cancer treatment." (PMID 32708166, 2020). "Our findings indicate that CHD1L plays a potential role in the inducement of EOC cancer cell invasion and/or metastasis via the regulation of METAP2 expression and suggests that CHD1L inhibition may provide a potential target for therapeutic intervention in human EOC." (PMID 32922205, 2020). "Interestingly, the enzyme MetAP2 is the biological target of the very well-known antiangiogenic compounds fumagillin and ovalicin, and their selectivities against MetAP2 is a key factor that is being explored, not only for the treatment of cancer but also for the development of antiobesity agents." (PMID 35736176, 2022). "We further set out to investigate whether the synergistic effect of PI3K inhibition and Metap1 or Metap2 knockdown is transferrable to cancer cells not originating from breast malignancies." (PMID 35673573, 2022). "Taken in the context of our results here on the function of CHD1L in EOC cells, these observations indicate that METAP2 might be a potential downstream target in the aggressive behavior of CHD1L-mediated EOC, and as a result promotes cancer cell invasion and metastasis." (PMID 32922205, 2020).